FUBP1 (far upstream element binding protein 1)
Diseases named in the same sentence as FUBP1 in open-access papers (continued):
Sharing a sentence is not in itself a finding about the gene and the disease.
tumor (continued). "Notably, the tumorigenicity of the sorted CD133+ALDH1+ LoVo cells was enhanced and fewer implantation of 1 × 105, 1 × 104, 1 × 103, or 1 × 102 cells were needed, meanwhile tumor size and tumorigenicity were quelled by FUBP1‐silence." (PMID 34288405, 2021). "Moreover, CRC cells (LoVo, SW620) derived from tumor metastasis showed higher expression of FUBP1 than those (CaCO2, HCT116, SW48) derived from the primary site." (PMID 34288405, 2021). "FUBP1 has been described paradoxically either as an oncoprotein or a tumour suppressor." (PMID 32778776, 2020). "Therefore, although it seems that anti-tumor agents would be effective in the suppression of cell cycling by weakening the Fubp1-cyclin A axis, anti-tumor drugs would be inefficient in tumor extinction due to downregulation of Fubp1." (PMID 32481602, 2020). "In particular, some of the most significant genes according to our approach, like FUBP1, NOTCH1, PTEN, EGFR, and NF1, were mutated in less than 10% of the patients within that tumor type, indicating that mutations in these genes are strongly associated with global changes in expression." (PMID 32732999, 2020). "FUBP1 is highly expressed in a variety of tumour tissues and cell lines." (PMID 31511046, 2019). "Our analysis illuminated a tumor evolutionary series of events, which included 1p/19q codeletion, IDH1 R132H, and TERT C250T as early events, followed by loss of function of NDST4 and mutations in FUBP1 and CIC as late events." (PMID 31217899, 2019). "In addition, FUBP1 upregulation was significantly correlated with the clinicopathological features of ccRCC, such as tumor size and stage." (PMID 28076379, 2017). "However, the only patient with a tumor harboring protein altering mutations in both CIC and FUBP1 died only three months after surgery." (PMID 24086756, 2013). "In conclusion, the high frequency and the spectrum of CIC mutations in our 1p/19q-codeleted tumor cohort support the hypothesis that CIC acts as a tumor suppressor in these tumors, whereas FUBP1 might play only a minor role." (PMID 24086756, 2013). "Interestingly, the one case that presented deleterious alterations in both CIC and FUBP1 (BT7) was the only recurrent tumor in our cohort, and the patient died only 3 months after surgery." (PMID 24086756, 2013). "In addition, FUBP1 homozygous deletion was detected in one case suggesting a putative tumor suppressor role of FUBP1 in AOD." (PMID 23071531, 2012). "The spatial/temporal distribution of FUBP1/CIC mutations may be heterogeneous, whereas the 1p/19q codeletion is homogeneously found within the tumor tissue, and a considerable number of 1p/19q codeleted tumors have no mutations to FUBP1/CIC." (PMID 27503138, 2016). "Interestingly, the primary tumor or xenografts did not expand in vitro, even though 1p/19q co-deletion with underlying mutations in both FUBP1 and CIC was present, as revealed by aCGH and exome sequencing." (PMID 23527265, 2013). "1p/19q status alone also may not be sufficient to determine whether a tumor contains alterations in CIC or FUBP1, since CIC mutation occurred in the absence of 1p/19q alteration in one of the cases studied." (PMID 22869205, 2012). "Using a tumour suppressor-targeting sgRNA library in MCF10F cells, one group identified far upstream binding protein 1 (FUBP1) as a long tail driver of breast cancer." (PMID 40650785, 2025). "We herein identified a sustained USP7 expression that, transcriptionally activated by FUBP1 and FUBP3, is essential for HIF2α stabilization and tumor progression in ccRCC." (PMID 39406703, 2024). "Mechanistically, USP7 expression is activated by the transcription factors FUBP1 and FUBP3, and it promotes tumor progression mainly by deubiquitinating and stabilizing HIF2α." (PMID 39406703, 2024). "Consistently, methylated FUBP1, PDK1, and SLC7A11 were also more robustly expressed in tumor tissues." (PMID 39146021, 2024).
tumor (continued). "Overexpression or knockdown of FUBP1 in CRC cells substantially enhanced or reduced the expression levels of CD133 and ALDH1, the formation of tumor sphere, thus affecting the ability of cell migration and invasion." (PMID 34288405, 2021). "Overexpression of FUBP1 significantly enhanced CRC cell migration, invasion, tumor sphere formation, and CD133 and ALDH1 expression in vitro, and tumorigenicity in vivo." (PMID 34288405, 2021). "High expression of FUBP1 usually leads to upregulation of c-MYC oncogene and disorder of the fine regulation of target proteins, which is one of main molecular mechanisms of tumor pathogenesis." (PMID 34116677, 2021). "Far upstream element binding protein 1 (FUBP1), a DNA-binding protein, participates in diverse tumor-promoting behaviors by regulating the expression of oncogenes in the nucleus, but the underlying mechanisms remain to be elucidated." (PMID 33987449, 2021). "In contrast, miR-16 acts as a tumor suppressor and can restore trastuzumab and lapatinib sensitivity by suppressing Cyclin J (CCNJ) and Far Upstream Element Binding Protein 1 (FUBP1) in resistant BC." (PMID 32967267, 2020). "Among them, the oncogene MYC is a well-known downstream target of FUBP1 and abnormal MYC overexpression mediated by FUBP1 has been consistently reported by several independent studies in various tumor types." (PMID 32481602, 2020). "It was found that miR-16 inhibited cell proliferation in BC cell lines and in tumor samples resistant to these drugs; this suggested a tumor suppressor role for miR-16, as it targets CCNJ (Cyclin J) and FUBP1 (Far Upstream Element Binding Protein 1)." (PMID 28574440, 2017). "In the cohort of resected patients, the Rho Spearman test showed a significant correlation between circulating aAb and upregulated expression in tumor tissue for FUBP1 (p = 0.0268), but not for ENO1 (p = 0.3172)." (PMID 37910256, 2023). "Moreover, FUBP1 increased the protein expression of DVL1 in CRC cells and tumor specimens, while silencing FUBP1 had the reverse effects." (PMID 34288405, 2021). "Unexpectedly, the RNA level of FUBP1 in the tumor tissues did not changed compared with adjacent tissues by analyzing the TCGA‐COAD database and remain consistent in the LoVo cell compared with the SW48 cell." (PMID 34288405, 2021). "It is possible that this combination of FUBP1 and CIC mutations, in the absence of other known major gene mutations, gave this particular tumor some kind of growth advantage upon intracranial implantation." (PMID 23527265, 2013). "Moreover, we revealed that FUBP1 protein expression was significantly upregulated in tumor tissues compared to non-cancerous tissues by IHC and immunoblots." (PMID 38233848, 2024). "For the FUBP1 knockdown tumor cells, the IC50 values were 10.69 μg/mL (MG63‐siRNA‐NC), 7.25 μg/mL (FUBP1 si#1), and 8.05 μg/mL (FUBP1 si#2) for the MG63 cells and 18.26 μg/mL (SOSP‐9607‐siRNA‐NC), 10.45 μg/mL (FUBP1 si#1), and 10.33 μg/mL (FUBP1 si#2) for the SOSP‐9607 cells." (PMID 37180822, 2023). "This indicates that high levels of anti-FUBP1 aAb mirror its high expression in PDA and prompted us to hypothesize that monitoring anti-FUBP1 aAb can be used to evaluate changes in FUBP1 tumor tissue expression and eventually target FUBP1 to reduce tumor burden." (PMID 37910256, 2023). "Dysregulation of FUBP1 expression is observed in a variety of cancers, although whether it is a tumor suppressor and oncogene are not entirely clear." (PMID 35963436, 2022). "FUBP1 can form a complex with the distal far upstream element (FUSE) site regulating gene expression, including c-Myc, p21, Usp29, etc., which displays a broad spectrum of activities, such as promoting proliferation, cell cycle, invasion and metastasis of tumour cells." (PMID 31511046, 2019). "Thus, FUBP1 and CIC variants appeared to occur secondary to the losses of 1p and 19q during tumor progression and were not necessary changes for tumor initiation in this case." (PMID 31217899, 2019).
tumor (continued). "Specifically, the cancer phenotypes could arise when XPB-dependent DNA repair defects alter hyperproliferative input(s); e.g., defective function of the FUBP1/FIR/TFIIH nexus would be predicted to disrupt repression of the MYC oncogene and contribute to XP-related neoplasia." (PMID 28398229, 2017). "The trunk alterations that existed throughout the course were restricted to IDH1 mutation, 1p/19q-codeletion, and TERT promoter mutation, and mutation of the known candidate tumor suppressor genes CIC and FUBP1 were not consistently observed between primary and recurrent tumors." (PMID 28270234, 2017). "The biological functions of FUBP1 in LUAD have not yet been reported, we, therefore, knocked down FUBP1 in A549 and Calu1 cells by siRNAs to assess potential changes in tumor cell phenotypes." (PMID 34274028, 2021). "Additionally, none of the putative tumor-suppressor genes relevant to LGG, namely, ATRX, CIC, FUBP1, and NOTCH1, showed correlations with overall survival (data not shown)." (PMID 27852048, 2017).
cancer (46 papers, 2013 to 2026). A tumor composed of atypical neoplastic, often pleomorphic cells that invade other tissues. "The association between DNA methylation of FUBP1 and the clinicopathological characteristics of different cancers was determined using MEXPRESS." (PMID 35274005, 2022). "FUBP1 was found to associate with Kpnβ1 in all three cancer cell lines, and to a lesser extent in the non-cancer cells." (PMID 36418423, 2022). "A hotspot residue within this protein mapped to the KH domain that has a role in nucleic acid recognition and is also a target of a hotspot mutation in the known cancer driver FUBP1." (PMID 29572294, 2018). "In addition, a significant positive correlation was observed between FUBP1 expression and the infiltration of cancer-associated fibroblasts in CESC, ESCA, HNSC, LIHC, LUSC, PAAD, and THYM with at least three different algorithms." (PMID 35274005, 2022). "Moreover, the infiltration of macrophages, neutrophils and cancer-associated fibroblasts was positively correlated with the expression of FUBP1 with at least two different algorithms." (PMID 35274005, 2022). "We additionally tested whether Fubp1 deficiency provides cells with survival advantages against anti-cancer drug as well." (PMID 32481602, 2020). "However, we also demonstrated the anti-tumorigenic role of Fubp1 by presenting that the loss of Fubp1 provides cells with survival advantages against metabolic stress and anti-cancer drugs." (PMID 32481602, 2020). "As a transcription-associated DNA helicase, dysregulation of the FUBP1 gene is a frequently occurring event in a multitude of malignancies and is associated with tumorigenesis and progression, and FUBP1 has increasingly become a novel pharmacological target for cancer treatment." (PMID 33987449, 2021). "In addition, we showed that Fubp1 deficiency confers survival advantages to cells against metabolic stress and anti-cancer drugs, suggesting that Fubp1 may play both positive and negative roles in malignant development." (PMID 32481602, 2020). "FUBP1 predominantly expressed in cancer cell nuclei was significantly increased in all four matching HGSOC relapse tissues compared to tissues at diagnosis." (PMID 40565351, 2025). "We evaluated 6 splicing factor mutations commonly observed in cancer, including hotspot mutations in SF3B1K700E, U2AF1S34F, and CRISPR-engineered loss of function in FUBP1, RBM5, RBM10, and ZRSR2." (PMID 41279721, 2025). "FUBP1 has been identified as a long tail cancer driver and globally affects the landscape of alternative splicing to create aberrant proteins that drive malignant transformation." (PMID 40757636, 2025). "We also developed a competitive peptide delivered by nanocomplexes to block FUBP1 methylation in vivo as a potential therapeutic approach for cancer treatment." (PMID 39146021, 2024). "In PDA cells, FUBP1 promotes cell proliferation, migration and regulates cancer cell immunity by increasing PD-L1." (PMID 37910256, 2023). "Mounting evidence confirmed that several potential candidates were overexpressed in certain cancers and contributed to glycolysis, including FUBP1, HIF-1α, and CD47." (PMID 37626036, 2023). "The most enriched GO items suggest the remarkable role of RNA splicing in the mechanism of FUBP1 across different cancer types, and the small-molecule splicing modulators that are currently in clinical trials offer a promising approach to cancer therapy." (PMID 35274005, 2022). "In summary, our first pan-cancer analyses of FUBP1 revealed remarkable correlations of FUBP1 with cancer driver events, such as protein phosphorylation, DNA methylation, genetic alteration, and the immune microenvironment." (PMID 35274005, 2022). "GO and KEGG enrichment analyses revealed the close relationship of FUBP1 with RNA splicing and the Cdc5L (cell division cycle 5-like protein) complex in all cancer types." (PMID 35274005, 2022).
cancer (continued). "Briefly, this pan-cancer analysis comprehensively revealed the multifaceted characteristics and oncogenic role of FUBP1 in different human cancers." (PMID 35274005, 2022). "Dysregulated FUBP1 expression was observed in most cancer types, and high FUBP1 expression suggests poor prognosis in cancers such as ACC, KICH, LIHC, LUAD, LUSC, SARC, CESC, and SKCM." (PMID 35274005, 2022). "Here, we are the first to investigate the putative oncogenic role of FUBP1 in 33 cancer types based on The Cancer Genome Atlas (TCGA) and Gene Expression Omnibus (GEO) databases." (PMID 35274005, 2022). "Human distal upstream element (Fuse) binding protein 1 (FUBP1) is a transcriptional regulator of c-Myc and represents an important prognostic marker in many cancers." (PMID 35546072, 2022). "Far upstream element-binding protein 1 (FUBP1) is reported to be involved in cancer development by regulating the transcription of c-myc gene through binding to far upstream element." (PMID 33954195, 2021). "Another protein, FUBP1, has been described as an oncoprotein in solid tumor entities as well as many other cancers, promoting tumorigenesis, proliferation, and metastasis of malignant cells." (PMID 33791202, 2021). "Meanwhile, the nuclear localization of FUBP1 was decreased when the M9M construct was expressed in cancer cells." (PMID 33987449, 2021). "In particular, the overexpression of FUBP1 has been observed in a growing number of cancers, leading to a deregulation of various targets, including the fine-tuned MYC oncogene." (PMID 34274028, 2021). "A positive correlation between FUBP1 mRNA and both of the hexokinases was found in several types of cancers." (PMID 33472578, 2021). "The expression of stemness‐related markers and the percentage of cancer stem cells were simultaneously upregulated in FUBP1‐transfected HCT116 cells, while conversely downregulated in FUBP1‐silenced SW620 cells." (PMID 34288405, 2021). "Overexpression of FUBP1 alters the expression of the oncogene MYC to promote cancer cell proliferation by interacting with FUBP interacting repressor (FIR) and transcription factor IIH (TFIIH)." (PMID 33987449, 2021). "FUBP1 overexpression was found in many cancers and led to a dysregulation of targets including MYC oncogene." (PMID 34116677, 2021). "Evidently, the expression of FUBP1 was commonly upregulated in several types of cancers as previously reported." (PMID 32481602, 2020). "Our data showed that Fubp1 deficiency provides cells with survival advantages against metabolic stress and anti-cancer drug, suggesting that Fubp1 has multiple functions in malignant development." (PMID 32481602, 2020). "Far upstream element binding protein 1 (FUBP1), a transcriptional activator of the c-myc gene, is activated in many cancers." (PMID 29796163, 2018). "Although FUBP1 had clinical importance in various cancers, and was shown to be the top-ranked TMZ-related gene in our microarray data." (PMID 29371945, 2017). "Despite several published reports that addressed the role of FUBP1 in promoting cancer development, little is known about its involvement in ccRCC." (PMID 28076379, 2017). "Also, the context-specific function and regulation of FUBP1 should be further investigated in other cancer types." (PMID 39146021, 2024). "Dysregulation of FUBP1 has been found in different cancer types." (PMID 39146021, 2024). "FUBP1, a multifunctional DNA- and RNA-binding protein, overexpressed in a number of cancers." (PMID 38233848, 2024). "Furthermore, the results from transwell migration and invasion assays revealed that FUBP1 knockdown attenuate the ability of tiRNA-Val-CAC-2 in promoting cancer cell migration and invasion." (PMID 38443680, 2024). "Given the importance of FUBP1 methylation to oncogenic progression, strategies to interfere with FUBP1 methylation might provide potential therapeutic approaches for cancer management." (PMID 39146021, 2024).